TNF (tumor necrosis factor)
Diseases named in the same sentence as TNF in open-access papers (continued):
Sharing a sentence is not in itself a finding about the gene and the disease.
pulmonary fibrosis (continued). "A previous study showed that overexpression of TNF-α induces mild pulmonary fibrosis in rats." (PMID 35082682, 2021). "Therefore, TNF modulators can potentially act as therapeutic targets in PQ-induced pulmonary fibrosis." (PMID 34580234, 2021). "Quercetin can reduce the expression of transforming growth factor-β1 (TGF-β1), α-smooth muscle actin (α-SMA), and tumor necrosis factor-α (TNF-α), inhibit alveolar cell apoptosis and reduce lung tissue inflammation and fibrosis injury in rats, which can effectively improve lung fibrosis." (PMID 33986661, 2021). "C/EBPβ also plays an important role in experimental lung fibrosis, as demonstrated by C/EBPβ null mice that developed less lung fibrosis after bleomycin injury due to the reduced production of lung pro-inflammatory cytokines TGFβ1, TNF-α, and IL-1β, and myofibroblast differentiation." (PMID 34207528, 2021). "Furthermore, we uncovered TNF signaling pathway and nine hub genes as potentially involved in PQ-induced lung fibrosis progression." (PMID 34580234, 2021). "It has been shown that macrophages, and inflammatory mediators, including IL-1β and TNF-α, could contribute to exacerbating lung fibrosis." (PMID 34399790, 2021). "In addition, intratracheal delivery of TNF-α facilitates the resolution of established pulmonary fibrosis induced by bleomycin." (PMID 35082682, 2021). "In addition, blocking TNF-α with quenching antibody attenuates pulmonary fibrosis induced by bleomycin and silica in mice." (PMID 35082682, 2021). "Moreover, it has been described that IL6, TNF-α, and IL-1β lead to activation of the NF-kB pathway, which is the major controller of pulmonary fibrosis and epithelial–mesenchymal transition, in response to chronic inflammation." (PMID 32660140, 2020). "The successful establishment of a mouse model with T2DM‐associated PTB was confirmed as inflammatory cell infiltration and increased pulmonary fibrosis, as well as increased production of pro‐inflammatory factors including TNF‐α, IL‐6 and IL‐1β in mouse lung tissues." (PMID 33089914, 2020). "Likewise, Thalidomide was able to reduce macrophages, and lymphocytes count in bleomycin (BLM)-induced pulmonary fibrosis mice model and to suppress IL-6, IL-8, TNF-α, and TGF-β levels in their bronchoalveolar lavage fluid (BALF)." (PMID 32574274, 2020). "MP infection can lead to the increase in pro-inflammatory cytokines, TNF-α and chemokine, such as IL-6 and promotes various leukocytes (mainly neutrophils) aggregation at the infection site, eventually resulting in lung injuries and pulmonary fibrosis." (PMID 32597476, 2020). "In addition, the inflammatory cytokines, including IL-6 and TNF-α, were markedly elevated in the mice lung tissues of the pulmonary fibrosis model and were dramatically inhibited by Hyp." (PMID 33192501, 2020). "Moreover, there is evidence that continued inflammation can decrease collagen deposition, whilst TNF-α has been shown to reduce the profibrotic collagen-dissolving activity of macrophages and pulmonary fibrosis." (PMID 33304918, 2020). "Therefore, EMT, NF-κB, and related inflammatory factors (TGF-β, TNF-α, and IL) are very important in the evaluation of pulmonary fibrosis." (PMID 33123215, 2020). "Moreover, studies have shown that paraquat can activate inflammatory related factors including TNFα, NF-κB, interleukin 1β, and IL-6, which in turn contribute to the development of pulmonary fibrosis." (PMID 33123215, 2020). "Moreover, TNF-α is involved in a wide range of inflammatory responses and silica-induced pulmonary fibrosis." (PMID 33817248, 2020). "The levels of IL-1, IL-6, and TNF-α in the bleomycin-induced mouse pulmonary fibrosis model were higher than those in the control group, while RC28-E treated mice showed a significant reduction in the levels of the proinflammatory cytokines IL-1, IL-6, and TNF-α in a concentration-dependent manner." (PMID 31652997, 2019).
pulmonary fibrosis (continued). "Moreover, progressive lung fibrosis has been indicated in patients with RA after treatment with infliximab (a TNF-α blocker)." (PMID 31881890, 2019). "The results of the present investigation are in accordance with previous findings where instillation of BLM caused ROS influx which in turn phosphorylated IκBα and activated NF-κB resulting in the release of pro-inflammatory cytokines (TNF-α, IL-1β, and IL-6) and brought out pulmonary fibrosis." (PMID 31611754, 2019). "Module 4 includes 34 genes, being associated with TNF and TCR signaling pathways and also involved in ER stress-related major (NF-kB survival signaling, lung fibrosis) and minor (AP-1 and HIF1α survival signaling, apoptosis, autophagy and inflammation) terms (green outlines)." (PMID 31523389, 2019). "Hesperidin alleviates BLM-induced IPF via inhibition of TGF-β1/Smad3/AMPK and IκBα/NF-κB pathways which in turn ameliorate the modulation of oxido-inflammatory markers (Nrf2 and HO-1) and pro-inflammatory markers (TNF-α, IL-1β, and IL-6) to reduce collagen deposition during pulmonary fibrosis." (PMID 31611754, 2019). "To investigate whether ERCs play an anti-inflammatory role in the development and progression of pulmonary fibrosis, we have measured the content of IL-1β, TNF-α, and IL-10 in the serum and the lung tissue." (PMID 30147727, 2018). "Increased TNF-α and IL-6 levels in serum and BALF are associated with lung fibrosis." (PMID 29849496, 2018). "We present evidence that IL-1-mediated skin and lung fibrosis depends on IL-17 activity and is associated with IL-6 and TNF-α activity, but not with TGF-β." (PMID 30042768, 2018). "SML is safe and effective in repressing BLM-induced pulmonary fibrosis, which might be through modulating the expression of TNF-α and TGF-β1." (PMID 29997685, 2018). "Numerous cytokines have been implicated in the pathogenesis of lung fibrosis, including transforming growth factor-β (TGF-β), tumour necrosis factor-α (TNF-α), platelet- derived growth factor (PDGF), insulin-like growth factor-1 (IGF-1), endothelin-1 (ET-1) and the interleukins, (IL)-1 and IL-8." (PMID 28974751, 2017). "Overexpression of TNF-α in mouse lungs resulted in spontaneous lung fibrosis." (PMID 27814727, 2016). "Besides VEGF TNF-α is overexpressed in early stages of pulmonary fibrosis and high TNF-α titers are furthermore correlated with a higher risk of developing a hepatic periportal fibrosis and stimulate the collagen synthesis in fibroblasts." (PMID 26807786, 2016). "Similarly, in a bleomycin-induced pulmonary fibrosis model, both fibrosis and alternative activation of macrophages are prolonged in TNF-α−/− mice." (PMID 26962470, 2015). "TNF-α is a proinflammatory cytokine that plays an important role in the activation of host defense and is associated with increased mortality in CHF patients and the development of pulmonary fibrosis." (PMID 26604970, 2015). "Conversely, treatment with TNF-α blockers significantly reduced lung fibrosis." (PMID 26596627, 2015). "An endotoxin-induced lung fibrosis model in mice showed an MSC-mediated reduction in pulmonary fibrosis via paracrine downregulation of pro-inflammatory responses by reducing TNF-α and macrophage inflammatory protein (MIP)-2 while increasing the anti-inflammatory interleukin (IL)-10." (PMID 26265166, 2015). "Moreover, our data also suggested that the protective effect of thalidomide against PQ-induced pulmonary fibrosis was associated with decreased expression levels of inflammatory factors such as TGF-β1, TNF-α and IL-6 in lung tissues after PQ exposure." (PMID 26221080, 2015). "Furthermore, in OVA-sensitized allergic rhinitis and bleornycin-induced pulmonary fibrosis murine models, TNFα antagonists have been shown to inhibit eosinophilia in the nasal mucosa and lung, respectively." (PMID 25400924, 2014).
pulmonary fibrosis (continued). "After a study on mouse lung tissue and lavage fluid, we found that dexamethasone can reduce inflammatory cell infiltration and decrease inflammatory cytokines related to lung fibrosis closely such as TNF-α, IL-6, and TGF-β1 protein expression in BALF in the 4th week, compared with the RT group." (PMID 24744681, 2014). "Indeed, experimental data indicate that key innate immune mediators (i.e. IL-12, TNF-α and type I interferons) and cells (i.e. DC and macrophages) are dispensable for the development of lung fibrosis in silica-treated mice." (PMID 25050810, 2014). "NNAV decreased IL-1β and TNF-α levels in serum in both pulmonary fibrosis models." (PMID 25465226, 2014). "IL-6 and TNF-α also play important roles in the pathogenesis of pulmonary fibrosis." (PMID 25216247, 2014). "Additionally, a number of studies proved that TNF-α was critical in the pathogenesis of pulmonary fibrosis, leading to pulmonary fibrosis via TGF-β1 production." (PMID 24300094, 2013). "They suggested a novel mechanism via which TNF-α could mediate pulmonary fibrosis through induction of IL-5-mediated eosinophil recruitment and fibrogenic cytokine production." (PMID 23997916, 2013). "It is therefore tempting to speculate that, for instance, the combined activity of LT and TNF-α, through induction of gp130-activating cytokines, indirectly promotes Stat3 signalling and the excessive matrix production that underpins lung fibrosis." (PMID 22684844, 2012). "Anti-TNF-α antibody attenuates BL-induced pulmonary fibrosis in mice." (PMID 21961991, 2011). "Previous studies have shown that blocking TGF-β and TNF-α may attenuate the development of pulmonary fibrosis." (PMID 21423633, 2011). "Tumor necrosis factor alpha (TNF-α) is important in the development of pulmonary fibrosis." (PMID 21961991, 2011). "With respect to pathogenesis of lung diseases, TNF-α may be responsible for several lung diseases such as pulmonary fibrosis, acute lung injury and pulmonary emphysema." (PMID 21961991, 2011). "In addition to IFN-γ, the classic proinflammatory cytokines IL-1β and TNF-α are increased in V2O5-induced lung fibrosis in mice and rats." (PMID 20738867, 2010). "In SSc, elevated TNF has been described in diffuse cutaneous patients with pulmonary fibrosis." (PMID 20808962, 2010). "Importantly, TNF-α and IL-1β are key cytokines that mediate injury inflammation and the subsequent fibrosis in experimental lung fibrosis triggered by bleomycin." (PMID 20657842, 2010). "Furthermore, these investigators were able to abrogate silica-induced inflammation and lung fibrosis with the administration of anti TNFα antibodies or TNFα receptors that antagonized the bioactive TNFα." (PMID 19479048, 2009). "In conclusion, this study demonstrates that reaction of quartz with AA increases toxicity of crystalline silica inducing a higher macrophage production of TNF-α, the pro-inflammatory cytokine currently believed to be mainly responsible for generation of lung fibrosis after exposure to silica." (PMID 19298665, 2009). "In the BLM-induced model of pulmonary fibrosis, inflammatory cytokines such as TNF-α increase immediately after BLM administration, and subsequently, levels of chemokines such as MCP-1, MIP-1α, and MIP-2 increase, resulting in the infiltration of inflamed cells into the lungs." (PMID 18500976, 2008). "Some treatments include mast-cell stabilizers to control their access to inflamed tissue and consequent cytokine production (IL-1, IL-6 and TNF-a); moreover, it has been suggested that treatment for idiopathic pulmonary fibrosis could benefit patients with PC19-PF." (PMID 40332501, 2025). "In addition, the cytokine storm contains an excess of pro-inflammatory markers including interleukins, monocyte attractant factors and tumor necrosis factor (TNF), several factors that have been described in chronic interstitial lung diseases such as idiopathic pulmonary fibrosis (IPF)." (PMID 39767799, 2024).
pulmonary fibrosis (continued). "In rodent models of lung fibrosis, mice exposed to BLM displayed increased expression of TNFα that was associated with TGFβ levels; moreover, adenoviral mediated TNFα overexpression in otherwise normal rat lungs resulted in upregulation of TGFβ1 and accumulation of αSMA expressing myofibroblasts." (PMID 37849737, 2023). "In addition, pro-inflammatory cytokines released by macrophages and potentially by neutrophils, mast cells and B-lymphocytes, e.g., TNFα and IL-1, may contribute to the regulation of lung fibrosis." (PMID 36768179, 2023). "The expression of TNF could not only trigger the initial acute inflammatory response to bleomycin-induced lung tissue injury, but also provide chronic inflammatory signals and lead to the progress of pulmonary fibrosis." (PMID 35548340, 2022). "In the BLM-induced model of pulmonary fibrosis, myeloid PTEN-deficient mice exhibited enhanced TGF-β1 activation and collagen deposition, decreased number of macrophages and T cells, and aberrant macrophage polarization with augmentation of various proinflammatory cytokines such as IL-6 and TNF-α." (PMID 35814272, 2022). "Moreover, monotherapy by L. minor protect the connective tissue deposition in the lungs which is evident from the statistically insignificantly decreased or commensurate to the control levels of the lung fibrosis-related IL-1β, IL-6, and TNF-α concentration, respectively." (PMID 35326173, 2022). "In current study, we firstly found that TNF-α related pathway could be the target of FZHY against lung fibrosis with informatic analysis, then FZHY was confirmed to inhibit the development of lung fibrosis in bleomycin-induced mice model, whereas methylprednisolone used as a positive control." (PMID 35548340, 2022). "Furthermore, IL-6 and TNF-α are strongly related to the development of lung fibrosis and EMT." (PMID 35463079, 2022). "Furthermore, the loss of AGER in the pulmonary fibrosis was induced by TGFB1 and TNF-alpha." (PMID 35185901, 2022). "However, evidence has emerged that the effects of IL-17 on pulmonary fibrosis may be temporally distinct from those of TNF-α." (PMID 34258628, 2021). "It has been demonstrated, for example, that the use of prednisone slowed the progression of lung fibrosis in rats, and that the mechanism of action could be related to increased levels of Cav-1, reduction in tumor necrosis factor (TNF-α), TGF-β, and platelet-derived growth factor (PDGF)." (PMID 35008594, 2021). "In addition, previous animal studies have indicated that RJ decreases the tissue levels of TNF-α in various pathological conditions, including cadmium chloride-induced testicular dysfunction, bleomycin-induced pulmonary fibrosis, and ethylene glycol-induced renal inflammation." (PMID 33050250, 2020). "MP infection can lead to proinflammatory cytokine, tumor necrosis factor-α (TNF-α), and chemokines, such as interleukin- (IL-) 6, promoting the recruitment of various leukocytes, primarily neutrophils, to the site of infection, eventually leading to lung injury and pulmonary fibrosis." (PMID 29849498, 2018). "Interestingly, anti-TNF-α therapy has been associated also with the new onset or exacerbation of ILD mainly in patients affected by RA, being the TNF-α, a vital cytokine implicated in the development of pulmonary fibrosis." (PMID 24600322, 2014). "As it was primarily considered a mitogen, anti-TNFα therapies have been evaluated in a variety of fibrotic disorders, but evidence suggests that these approaches may exacerbate disease severity, notably in pulmonary fibrosis." (PMID 24641440, 2014). "Therefore, the main task of future research is to regulate the content and levels of TGF-β and TNF-α by molecular biology methods such as biological modifiers, gene therapy and stem cell transplantation, to manipulate and mini-mise radiation-induced pulmonary fibrosis and injury." (PMID 23407465, 2013).
pulmonary fibrosis (continued). "On the other hand, mice KO for TNFα develop a bleomycin-induced pulmonary fibrosis that may be reverted by the administration of TNFα; TNF-α is also able to block the synthesis of collagen production and inhibits α2 collagen gene transcription in human dermal fibroblasts." (PMID 22229089, 2011). "In addition, a soluble receptor for TNF-α alleviates BL-induced pulmonary fibrosis." (PMID 21961991, 2011). "Since chronic overexpression of TNF-α alone did not produce pulmonary fibrosis, we hypothesized that chronic overexpression of TNF-α might make the lungs more susceptible to BL or TGF-β1." (PMID 21961991, 2011). "Studies have shown that RRAS can inhibit the secretion of inflammatory mediators such as TNFα and CCL2 by endothelial cells, reduce fibroblast activation, and alleviate pulmonary fibrosis." (PMID 40002743, 2025). "Mouse PCLS were exposed to either 10 μM nicotine, 10% cigarette smoke extract (CSE), or a fibrosis-inducing cocktail (FC) containing TGF-β, PDGF-BB, TNF-α, and LPA, which are known mediators of lung fibrosis." (PMID 39958688, 2025). "In idiopathic pulmonary fibrosis (IPF), alveolar epithelial cell injury leads to the release of interleukin-1 (IL-1), tumor necrosis factor-alpha (TNF-α), and chemokine CCL2." (PMID 41007870, 2025). "Critically, our study extends this paradigm to pulmonary fibrosis: FSTL1 overexpression in A549 cells amplified NF-κB and cytokines (IL-1β/TNF-α/IL-6), FSTL1 inhibition attenuated TGF-β1-induced inflammation." (PMID 40808692, 2025). "The levels of TNF-α, IL-1β, and IL-6 expression were enhanced in PM10-induced pulmonary fibrosis (p < 0.05)." (PMID 40299673, 2025). "Inflammatory cytokines, including TNF-α, IL-1β, IL-6, and TGF-β1, are recognized to play a role in the initiation and progression of pulmonary fibrosis." (PMID 40665395, 2025). "In vitro experiments indicated that SM injection alleviated pulmonary fibrosis by downregulating MMP9, IL-6, and TNF-α." (PMID 40630478, 2025). "Benchmarking the effect of cytokine-targeting drugs (anti-TNF-α, anti-PDGF, anti-IL-13, anti-TGF-β) on pulmonary fibrosis progression." (PMID 38550585, 2024). "To characterize the kinetic effects of 2 U/kg i.t. bleomycin on various biochemical markers of lung fibrosis, we measured the concentrations of TGFβ1, IL6, TNFα, IL1β, CINC1, WISP1, VEGF, and TIMP1 in BALF at days 3, 7, and 14 following instillation." (PMID 38534359, 2024). "The pathogenesis of pulmonary fibrosis involves various mediators such as TGF-β, legumain, osteopontin, IL-4, IL-6, IL-13, IL-17, TNF-α, Gal-1, Gal-3, PDGF, and FGFR-1." (PMID 38540252, 2024). "The authors explored the efficacy of four therapies (anti-TNF-α, anti-PDGF, anti-IL13, anti-TGF-β) and showed that only targeting TGF-β should result in a beneficial effect on pulmonary fibrosis." (PMID 38550585, 2024). "Conversely, depletion of TRIM33 leads to increased production of TGF-β1, inducing idiopathic pulmonary fibrosis (IPF) and interstitial lung inflammation through Smad4 and downstream inflammatory factors such as TNF-α and IL-6." (PMID 37415133, 2023). "Anti-inflammatory agents targeting pro-inflammatory cytokines, such as TNF-α, IL-1, and TGF-β, and anti-fibrotic drugs, including pirfenidone and nintedanib have been explored as potential treatments for pulmonary fibrosis in addition to antioxidant therapies." (PMID 37371940, 2023). "In particular, during the initial phases of the fibrotic process, NF-κB increases the expression of genes coding for the synthesis of many inflammatory cytokines, such as TNFα, IL6, IL1β and TGFβ, essential for the development of pulmonary fibrosis." (PMID 37626373, 2023). "Our analysis showed that CC-11050 treatment significantly downregulated the expression TNF-α and recruitment of TNF-α + macrophages to the lungs, with a concomitant decrease in lung fibrosis and fibroblast cell activation in the SARS-CoV2 infected hamsters." (PMID 37854602, 2023).